PHF3 (PHD finger protein 3)
Tractability: PROTAC: UniProt records ubiquitination sites on it; ubiquitination databases record sites on it; its protein half-life has been measured.
Gene: Protein-coding gene on chromosome 6 (63,635,802 to 63,779,336, forward strand). Ensembl gene ENSG00000118482.
Subcellular location (Human Protein Atlas): Nucleoplasm
Gene Ontology:
Biological process: DNA-templated transcription
Genetic constraint (gnomAD): Loss-of-function variants: 35 observed, 153.99 expected, observed/expected ratio (o/e) 0.23, 90% interval 0.17 to 0.3. The upper end of that interval is the gene's LOEUF score, 0.3, which puts it in group 1 of 6, group 1 being the genes least tolerant of losing a copy. Missense variants: 2,240 observed, 2,345.9 expected, observed/expected ratio (o/e) 0.95, 90% interval 0.92 to 0.99. Synonymous variants: 790 observed, 793.86 expected, observed/expected ratio (o/e) 1, 90% interval 0.94 to 1.05.
Homologues: Orthologues: chimpanzee PHF3 (99% identical), macaque PHF3 (97% identical), dog PHF3 (88% identical), rabbit PHF3 (87% identical), pig PHF3 (85% identical), rat Phf3 (79% identical), mouse Phf3 (79% identical), zebrafish phf3 (28% identical), tropical clawed frog phf3 (27% identical). Paralogues in human: DIDO1 (21% identical), SPOCD1 (12% identical).
Diseases named in the same sentence as PHF3 in open-access papers:
PHF3 is named in the same sentence as 16 diseases in open-access papers, as found by Europe PMC text mining. Sharing a sentence is not in itself a finding about the gene and the disease. The quoted sentences say what the papers report.
glioblastoma (5 papers, 2014 to 2023). The most malignant astrocytic tumor (WHO grade IV). "Importantly, Bye1 has two human homologues possessing the same domain organization: PHF3 and the Dido gene encoding three proteins Dido1, 2 and 3, described as putative transcription factors and abnormally expressed in glioblastoma and myeloproliferative disorders." (PMID 25029256, 2014). "Our data suggest that PHF3 downregulation may drive glioblastoma via derepression of transcription factors that regulate neuronal differentiation." (PMID 34667177, 2021). "Additionally, the block spanned PHF3 is involved in glioblastoma development." (PMID 32151281, 2020). "In glioblastomas, the growing list of candidate TAAs include the epidermal growth factor receptor (EGFR), tenascin-C (TNC), fatty acid binding protein 5 (FABP5), melanoma-associated antigen 3 (MAGEA3), glioma-expressed antigen 2 (GLEA2), and PHD finger protein 3 (PHF3)." (PMID 25944688, 2015).
alcohol dependence (2 papers, 2011 to 2018). Physical and psychological dependence on alcohol. "We conclude that the PHF3-PTP4A1 region appears to harbor a causal locus for alcohol dependence, and proteins encoded by PHF3 and/or PTP4A1 might play a functional role in the disorder." (PMID 22096494, 2011). "This might suggest that the majority of the functions of PHF3-PTP4A1 contributed to the risk for alcohol dependence, and that the regulatory pathway via which these SNPs caused alcohol dependence might be related to the PHF3 and PTP4A1 proteins per se." (PMID 22096494, 2011). "Expression of PHF3 and PTP4A1 transcripts was significantly correlated with expression of many alcoholism-related genes in brain, including those in the dopaminergic, serotoninergic, GABAergic, glutamatergic, histaminergic and endocannabinoid systems." (PMID 22096494, 2011). "PHF3 and PTP4A1 might also influence alcohol dependence by interacting with other genes." (PMID 22096494, 2011).
glioma (2 papers, 2012 to 2023). A benign or malignant brain and spinal cord tumor that arises from glial cells (astrocytes, oligodendrocytes, ependymal cells). "Several authors have already applied SEREX to glioma, and some antigens, including glioma-expressed antigen 2 (GLEA2), PHD finger protein 3 (PHF3), and SRY-box 6 (SOX6) have been identified." (PMID 23050879, 2012).
alcohol abuse (1 paper, 2011). The use of alcoholic beverages to excess, either on individual occasions ("binge drinking") or as a regular practice. "It has been reported that alcohol abuse could significantly up-regulate the gene expression level of PHF3 in the frontal cortex in alcoholics." (PMID 22096494, 2011).
cutaneous melanoma (1 paper, 2023). A primary melanoma arising from atypical melanocytes in the skin. "PHF3 is also significantly amplified in the TCGA cutaneous melanoma cohort." (PMID 36977461, 2023).
depression (1 paper, 2018). "Some PHF3 paralogs have been shown to be linked with depression and modulate stress response." (PMID 30571770, 2018).
melanoma (1 paper, 2023). A malignant, usually aggressive tumor composed of atypical, neoplastic melanocytes. "PHF3 has previously been associated with UV DNA damage response in melanoma; however, here, it appears to be a clonal driver of a non–sun-exposed melanoma, suggesting a potential alternative role for PHF3 in melanoma progression, warranting further investigation in larger cohorts." (PMID 36977461, 2023). "Interestingly, CRUKP2986 was a case of a non-UV–exposed melanoma, suggesting a potential alternative function for PHF3 here." (PMID 36977461, 2023).
cancer (2 papers, 2014 to 2025). A tumor composed of atypical neoplastic, often pleomorphic cells that invade other tissues. "The BYpass of Ess1 (Bye1) protein is a putative S. cerevisiae transcription factor homologous to the human cancer-associated PHF3/DIDO family of proteins." (PMID 25029256, 2014).
neurodevelopmental disorder (2 papers, 2023 to 2024). A behavioral and cognitive disorder with onset during the developmental period that involves impaired or aberrant development of intellectual, motor, or social functions. "Potentially damaging CNVs (pdCNVs) provided support to the involvement of inherited variants in PHF3, NEGR1, TIAM1 and HOMER1 in neurodevelopmental disorders (NDD), although mostly acting as susceptibility factors with incomplete penetrance." (PMID 37961520, 2023).
tumor (2 papers, 2025 to 2026). "Prophylactic mPhf3-DC vaccination, based on the mutated PHF3 peptide (mPHF3), can suppress ASB-XIV tumor progression by eliciting mPHF3-specific CD8+ T cell responses within the local tumor microenvironment, which mediate anti-tumor immunity." (PMID 40563603, 2025).
PHF3 also shares sentences with these, for which no sentence is quoted: autism (2 papers); alcoholism (1); benign glioma (1); ciliary dyskinesia (1); developmental delay (1); myeloproliferative disorder (1).